HRAS (HRas proto-oncogene, GTPase)
Diseases named in the same sentence as HRAS in open-access papers (continued):
Sharing a sentence is not in itself a finding about the gene and the disease.
cancer (continued). "One of the most frequent carcinogenic chemicals is methyl nitrosourea, which targets the second base on the 12th codon of HRAS and KRAS, generating a G12D mutation in many cancer types." (PMID 40002297, 2025). "RAS genes, such as HRAS, KRAS, and NRAS, were the first identified human oncogenes and are mutated frequently in cancer." (PMID 39455281, 2025). "As a result, ~19% of cancer patients harbor a RAS mutation, with KRAS accounting for 75% of RAS-mutant cancers, while NRAS (17%) and HRAS (7%) are associated with a smaller subset." (PMID 40801144, 2025). "KRAS, NRAS, and HRAS are the three main isoforms affected in cancer; among them, KRAS is the most frequent gain-of-function mutation, occurring in up to 90% of pancreatic cancer, 50% of colorectal cancer, and 30% of lung adenocarcinoma." (PMID 40970755, 2025). "Research indicates that ROS can influence tumorigenesis and cellular transformation by oxidizing cysteine residues, which subsequently activate the three most prevalent oncogenic switch genes in human cancers: HRAS, NRAS, and KRAS." (PMID 40181979, 2025). "Among the RAS oncogene family, which includes KRAS, HRAS, and NRAS, KRAS is the most frequently mutated, accounting for ∼30% of all RAS-driven cancers, while HRAS and NRAS mutations are less common, occurring in ∼8% and ∼3% of cases, respectively." (PMID 40563459, 2025). "Curiously, this order correlates with that of their exploitation in cancer, where KRAS is most and HRAS least frequently mutated." (PMID 41248180, 2025). "Neither of the mutations identified in our patients (BRAF p.V600E or HRAS p.G13R) has been previously published in DICER1-associated malignancies, despite being bona fide driver mutations in other cancers." (PMID 40634537, 2025). "These aspects are a challenge to the penetration of PDAC and delivery of therapies, such as antibodies.The RAS protein is frequently mutationally activated (HRAS, KRAS, and NRAS) in human cancer." (PMID 40002297, 2025). "We investigated the frequency of RAS mutations (KRAS, NRAS, HRAS) in different cancer types using the C-CAT database, a Japanese national cancer genome database." (PMID 40970755, 2025). "BAY 11-7082, an inhibitor of IκBα kinase, attenuates the growth of NRAS, KRAS, and HRAS mutant cancer cells in cell culture and in mouse model." (PMID 38982514, 2024). "Regarding HRAS mutant cancer cells, the downregulated pathways via Kegg enrichment analysis included Wnt signaling, hypoxia-inducible factor 1 (HIF-1) signaling, glucagon signaling, Prolactin signaling, and Hippo signaling, among others." (PMID 38982514, 2024). "In particular, HRAS and KRAS proto-oncogenes are good archetypes representing one of the most frequent oncoproteins associated with human cancer, with ∼20% of cancers driven by one or multiple point mutations in these genes." (PMID 39722416, 2024). "Four isoforms of the RAS protein are found in humans: HRAS, NRAS, KRAS4A, and KRAS4B, with RAS mutations detected in 19% of cancer patients (75% in KRAS, 17% in NRAS, and 7% in HRAS)." (PMID 39301544, 2024). "RAS genes (KRAS, HRAS, NRAS) are the most frequently mutated oncogene family, with mutations occurring in 19% of patients with cancer." (PMID 38800401, 2024). "We next measured the apoptosis induction using annexin V and PI staining method and found a significant increase in apoptosis induction in NRAS, KRAS, and HRAS mutant-cancer cell lines upon treatment with BAY 11-7082 as compared to DMSO treated cells." (PMID 38982514, 2024). "Regarding HRAS mutant cancer cells, the downregulated pathways included Wnt signaling, HIF-1 signaling, glucagon signaling, Prolactin signaling, and Hippo signaling." (PMID 38982514, 2024). "For decades, pervasive dogma in the field was that all mutations in all three cancer-relevant RAS isoforms (KRAS, HRAS, and NRAS) were functionally equivalent." (PMID 38800401, 2024).
cancer (continued). "Combined analysis of n = 1079 human cancer cell lines (> 25 lineages) showed that activating mutations in KRAS, NRAS and HRAS correlate significantly with increased c-RAF gene dependency vs. wild-type RAS." (PMID 38637546, 2024). "We subsequently evaluated BAY 11-7082’s efficacy in inhibiting the tumorigenic potential of cancer cells expressing oncogenic NRAS, KRAS, and HRAS mutations." (PMID 38982514, 2024). "The RAS gene family encodes four protein isoforms (KRAS4A, KRAS4B, HRAS, and NRAS), all of which are frequently mutated in various cancer types, including solid tumors and hematological cancers." (PMID 39056802, 2024). "Mutations in the HRAS and NRAS have also been observed in other cancer types, including head and neck, bladder, and skin cancers." (PMID 39456601, 2024). "We further conducted RNA sequencing analyses to identify novel genes and pathways altered by BAY 11-7082 treatment in context of NRAS, KRAS, and HRAS mutant cancer cells which leads to tumor growth inhibition." (PMID 38982514, 2024). "The molecular genetic somatic mutation research in cancer plays an essential role and the presence of mutated genes that belong to the Ras subfamily (e.g., KRAS, NRAS, HRAS) allows for the detection of several cancer types." (PMID 38539435, 2024). "In summary, all the pathways identified to be downregulated in NRAS, KRAS, and HRAS mutant cancer cell lines upon BAY 11-7082 treatment are prooncogenic and have shown to promote different aspects of tumor growth and progression." (PMID 38982514, 2024). "The RAS genes which code for KRAS, HRAS, and NRAS are three of the most frequently mutated oncogenes responsible for cancer deaths." (PMID 39184150, 2024). "We observed similar results, namely BAY 11-7082 treatment leads to significant increase in PARP-cleavage in NRAS, KRAS, and HRAS mutant-cancer cell lines." (PMID 38982514, 2024). "The RAS family proto-oncogenes (KRAS, NRAS, HRAS) play a crucial role in cellular signaling and cancer biology." (PMID 39001451, 2024). "The BAY 11-7082 treatment exerts a broad-spectrum impact, mechanistically altering various pathways in cancer cells harboring NRAS, KRAS, and HRAS mutations." (PMID 38982514, 2024). "It will provide a versatile solution to the genetic heterogeneity observed in different cancers harboring HRAS, NRAS, and KRAS, making it a valuable tool to treat various malignancies with RAS mutations." (PMID 38982514, 2024). "We found that PI3K-AKT signaling pathway was significantly inhibited in NRAS, KRAS, and HRAS mutant-cancer cell lines upon treatment with BAY 11-7082 as observed by reduced p-AKT protein level." (PMID 38982514, 2024). "The proliferation of HRAS-mutant cancer cell lines Hs 578 T and T24 was specifically reduced by TAT-L5URcore, but not the control TAT-peptides." (PMID 38982284, 2024). "It is the most frequently mutated isoform in human cancers (85%), followed by NRAS (11%) and HRAS (3%)." (PMID 39056802, 2024). "Activation of the RAS/MAPK pathway, driven by mutations like HRAS (G12V) and BRAF (V600E), is significant in resistance and metastasis in HH-dependent cancers." (PMID 39568072, 2024). "Results indicated a significant, concentration-dependent reduction in tumor-forming potential of cancer cells expressing oncogenic NRAS, KRAS, and HRAS mutations upon treatment with BAY 11-7092." (PMID 38982514, 2024). "Based on our model and mechanistic data, signaling, and proliferation of HRAS mutant cancer cell lines with high Gal1 levels were expected to respond best to the nanocluster disrupting TAT-L5URcore peptide." (PMID 38982284, 2024). "Studies have shown that increased TRPML1 expression and activity in HRAS-driven cancer cells are crucial for cholesterol localization in the cell membrane, while TRPML1 inhibition reduces ERK phosphorylation and cell proliferation." (PMID 38672219, 2024).
cancer (continued). "Research on HRAS and its role in cancer remains an active area of investigation, with ongoing efforts to identify new mutations and decipher their functional consequences." (PMID 37153521, 2023). "Genes in the RAS family (HRAS, KRAS, NRAS) represent the most frequently mutated oncogenes in human cancers, accounting for 3.4 million cancer diagnoses each year." (PMID 37655310, 2023). "RAS (HRAS, KRAS, and NRAS) is the most frequently mutated gene in human cancers, particularly in positions G12 and Q61, and, consequently, the inhibition of oncogenic signaling mediated by RAS has been a key challenge in the field of cancer biology." (PMID 37627277, 2023). "Other studies examining the programs of splicing regulation in cancer have also identified HRAS as a MYC-dependent exon." (PMID 37399401, 2023). "KRAS, HRAS, and NRAS are the three most commonly mutated RAS isoforms with varying mutation rates in different cancers." (PMID 37662925, 2023). "RAS (HRAS, KRAS, and NRAS), as the second largest mutated gene driver in various human cancers, has long been a vital research target for cancer." (PMID 37704624, 2023). "Among all cancer types, more than half of all HRAS-mutant cancers had co-altered lesions, with the exception of those of thyroid and prostate." (PMID 37503077, 2023). "Using targeted sequencing data from MSK-IMPACT and DFCI-GENIE databases we identified co-mutations in HRAS- vs KRAS- and NRAS-mutant cancers." (PMID 37503077, 2023). "The receptor tyrosine kinase/RAS/MAP kinase (MAPK) pathway is an oncogenic pathway with widespread aberrancies in human cancers; indeed, 20%-30% of cancer patients harbor RAS (KRAS, HRAS, or NRAS) mutations." (PMID 37705755, 2023). "RAS genes (KRAS, HRAS and NRAS) comprise the most frequently mutated oncogene family in human cancer." (PMID 37807065, 2023). "Our research provides compelling evidence for the potential functional role of nsSNPs in up-regulating HRAS expression and contributing to the development of various types of cancers." (PMID 37153521, 2023). "HRAS, referred to as oncogenic RAS with NRAS and KRAS, is one of the most frequently mutated driver proto-oncogenes in cancer." (PMID 36906552, 2023). "Among the RAS protein family, KRAS is the most frequently mutated protein in human cancer, followed by NRAS and HRAS." (PMID 37895906, 2023). "We investigate the potential impact of nsSNPs in the HRAS gene on the structure and function of the HRAS protein, as well as their potential contribution to the development of various types of cancers." (PMID 37153521, 2023). "The isolation of the first human oncogene (HRAS), a critical breakthrough in cancer research, has occurred over forty years ago, and the identification of new pathogenic oncogenes has continuously grown since [...]." (PMID 37108381, 2023). "This group suggested that the potent oncogenicity of HRAS lead to cell cycle arrest and senescence, while the different codon usage of KRAS overcomes this issue becoming the most frequently mutated RAS in cancer." (PMID 37892237, 2023). "Considering the Afirma Gene Expression Classifier and ThyroSeq genomic classifier are not yet available in China and are expensive, 5 of the most common cancer-associated somatic mutations (BRAF, HRAS, NRAS, KRAS and TERT) were offered in our hospital." (PMID 36737779, 2023). "The intricate protein-protein interaction network between HRAS and its downstream effectors in cancer cells comprises several signaling molecules, kinases, and transcription factors that are essential for malignant transformation and disease progression." (PMID 37153521, 2023). "Our findings indicated that the G60V, G60D, and D38H mutants had higher binding energies than the wild-type HRAS protein, potentially leading to the activation of oncogenic signalling pathways and contributing to the development of various types of cancers." (PMID 37153521, 2023).
cancer (continued). "KRAS, HRAS, and NRAS are oncogenes that are frequently mutated human cancers, with KRAS mutations being the most prevalent, forming 85% of all RAS mutations and affecting about 13% of cancer patients." (PMID 37395796, 2023). "The clinical development of farnesyltransferase inhibitors (FTI) for HRAS-mutant tumors showed mixed responses dependent on cancer type." (PMID 37503077, 2023). "The ratio of wild-type:mutant RAS alleles requires further study as a biomarker for FTI sensitivity of HRAS-mutant cancers." (PMID 37503077, 2023). "In summary, results from our study highlight the importance of co-altered mutations and of wild-type RAS in driving resistance to targeted therapy of HRAS-mutant cancers." (PMID 37503077, 2023). "Variants in three genes (RPN1, HRAS and PALB2) were carried by several individuals with cancer in extended cohort." (PMID 36845707, 2023). "RAS is the most common oncogene in cancer, and KRAS mutations are the predominant oncogene among the three RAS subtypes (HRAS, NRAS, and KRAS), which was regarded as “untreatable” targets for a long time." (PMID 35281897, 2022). "Based on a recent publication evaluating several leading cancer mutation databases, KRAS is by far the most commonly mutated of the three RAS genes in solid tumours (75%), followed by NRAS (17%) and HRAS (7%)." (PMID 35621690, 2022). "RAS is the most frequently mutated oncogene in cancer, and it includes KRAS, HRAS, and NRAS subtypes of which KRAS is commonly seen in cancer." (PMID 35685832, 2022). "Despite the evidence for a functional role of mutant KRAS–AGO2 interaction in cellular transformation and proliferation, the role of AGO2 in mutant HRAS or NRAS cancers is unclear." (PMID 35923912, 2022). "The HRAS gene belongs to the group of RAS GTPases that play an important role in the development of many types of cancer." (PMID 36012171, 2022). "Among therapeutic strategies targeting HRAS-mutant cancers, tipifarnib, a farnesyl transferase (FT) inhibitor, is one of the most promising candidates." (PMID 35621690, 2022). "Mutations in HRAS and NRAS account for approximately 4% and 11% of all RAS-driven cancers, respectively." (PMID 35923912, 2022). "NRAS, along with KRAS and HRAS, constitutes the RAS family, which is the most frequently mutated gene family in cancer." (PMID 36003381, 2022). "KRAS is the most frequently mutated isoform among the RAS family of genes and is associated with an overall percentage of 75–83% of all RAS-mutated cancers, whereas NRAS is detected in only 8–17% and HRAS in 3–7% of all cases." (PMID 36359850, 2022). "The NRAS gene and its family KRAS and HRAS have been explained to be related to different types of cancers." (PMID 36430761, 2022). "The three RAS oncogenes (HRAS, KRAS and NRAS) are part of the most frequently mutated gene family in human cancer, since over 20% of human cancers harbor mutations in one of the three RAS genes, making them the most prevalent oncogenic drivers." (PMID 35456940, 2022). "Since the finding of HRAS as the first human oncogene, we have learned that the RAS gene family appears as the most frequently mutated in human cancer: 22%, 8.2% and 3.7% for KRAS, NRAS and HRAS, respectively." (PMID 36358912, 2022). "Mutations in proto-oncogenes (e.g., KRAS, HRAS) and tumor-suppressor genes (e.g., APC, PTEN) are the primary drivers in various cancers." (PMID 36553455, 2022). "It is also druggable, farnesyl transferase inhibitors (FTIs) that mislocalize HRAS are showing promising results in clinical trials on HRAS mutant cancers." (PMID 36065754, 2022). "In CRC, KRAS is the most frequent isoform mutation, accounting for about 20% of all human cancers, while neuroblastoma rat sarcoma (NRAS) and Harvey rat sarcoma (HRAS) mutations are found in about 8% and 3% of cancers, respectively." (PMID 35454852, 2022).
cancer (continued). "Given the exclusive reliance of HRAS proteins on FTase for membrane localization and activity, FTase inhibition has emerged as an attractive therapeutic strategy for HRAS-driven cancers." (PMID 35459782, 2022). "Four RAS proteins from this superfamily (HRAS, NRAS, KRAS4A, and KRAS4B), encoded by three RAS genes (HRAS, NRAS, and KRAS), are commonly mutated in and drive the initiation and progression of several human cancers." (PMID 35839996, 2022). "Activating mutations in KRAS, HRAS, and NRAS occur in over 30% of all cancers, with particular prevalence in pancreatic, melanoma, multiple myeloma, and colon cancers." (PMID 35923912, 2022). "KRAS is the most frequently mutated (85% of all RAS-driven cancers), followed by NRAS (12%) and HRAS (3%) (COSMIC v80)." (PMID 35456940, 2022). "The three mammalian RAS genes (HRAS, NRAS and KRAS) encode four proteins that play central roles in cancer biology." (PMID 36393833, 2022). "HRAS, NRAS, and KRAS, collectively referred to as oncogenic RAS, are the most frequently mutated driver proto‐oncogenes in cancer; the relationship between oncogenic RAS and ferroptosis is still controversial." (PMID 34878732, 2022). "Three RAS genes, HRAS, NRAS, and KRAS, are the most frequently mutated oncogenes in cancer, with the most paramount mutation being the KRAS mutation." (PMID 35281897, 2022). "Abnormal activation of Ras proteins (including RRAS2, MRas, HRas, KRas, and NRas) is the primary stimulus of oncogenes that has an essential role in the main signaling pathway in cancer." (PMID 36251702, 2022). "Clear examples are missense mutations in classic RAS genes (KRAS, HRAS and NRAS) that underlie the development of approximately 13% of human cancers." (PMID 35120522, 2022). "The Harvey rat sarcoma (HRAS) proto-oncogene belongs to the RAS family and is one of the pathogenic genes that cause cancer." (PMID 36358305, 2022). "Mutations in one of the three RAS genes (HRAS, KRAS, and NRAS) are present in nearly 20% of all human cancers." (PMID 36334633, 2022). "Nearly all factors of the RAS pathway are altered in cancer, most frequently activating mutations of KRAS, NRAS, HRAS, BRAF and receptor tyrosine kinases (RTKs)." (PMID 35456940, 2022). "KRAS, HRAS and NRAS, the three subsets of RAS, are well known to be activated by mutation in nearly a quarter of all human cancers, of which KRAS plays a key role in driving tumorigenesis." (PMID 35422066, 2022). "The HRAS gene has been annotated in the cell proliferation of several carcinomas; however, the in silico analysis understanding of the structural and functional effect of deleterious nsSNPs has remained uncharacterized." (PMID 36358305, 2022). "Evidence for LOH as a frequent event in cancer initiation has been observed in model systems for all three RAS genes (HRAS, NRAS, KRAS)." (PMID 33924994, 2021). "The most frequent mutated oncogene family in the history of human cancer is the RAS gene family, including NRAS, HRAS, and, most importantly, KRAS." (PMID 34638560, 2021). "Estrogen has been shown to induce c-HRas expression via activation of tyrosine kinase in uterine endometrial fibroblasts and cancer cells, wherein estrogen increased c-HRas expression and tyrosine kinase activity in both fibroblast and Ishikawa cells." (PMID 34502029, 2021). "Several studies have found that the WT allele corresponding to the specific mutated RAS gene (WT HRAS in HRAS-mutated cancers; WT NRAS in NRAS-mutated cancers; WT KRAS in KRAS-mutated cancers) suppresses tumorigenesis." (PMID 33924994, 2021).